SPATA31A3 (SPATA31 subfamily A member 3)
Description:
May play a role in spermatogenesis.
Synonyms: FAM75A3; OTTHUMG00000013164; DKFZp434B204
Tractability: Antibody: UniProt predicts a signal peptide or a membrane-spanning region.
Gene: Protein-coding gene on chromosome 9 (66,986,304 to 66,992,550, reverse strand). Ensembl gene ENSG00000275969.
Subcellular location: Membrane
Subcellular location (Human Protein Atlas): Acrosome; Equatorial segment
Gene Ontology:
Cellular component: membrane
Genetic constraint (gnomAD): Loss-of-function variants: 0 observed, 2.84 expected, observed/expected ratio (o/e) 0, 90% interval 0 to 1.03. That is too few expected variants to judge how well the gene tolerates losing a copy. Missense variants: 103 observed, 408.34 expected, observed/expected ratio (o/e) 0.25, 90% interval 0.21 to 0.3. Synonymous variants: 33 observed, 143.21 expected, observed/expected ratio (o/e) 0.23, 90% interval 0.17 to 0.31.
Homologues: Orthologues: mouse Spata31 (28% identical), rat Spata31 (28% identical). Paralogues in human: SPATA31A5 (99% identical), SPATA31A7 (99% identical), SPATA31A1 (98% identical), SPATA31A6 (98% identical), SPATA31C1 (76% identical), SPATA31C2 (73% identical), SPATA31E1 (34% identical), SPATA31D1 (27% identical), SPATA31D3 (18% identical), SPATA31D4 (18% identical), SPATA31F1 (17% identical), SPATA31F3 (2% identical).